MTOR (mechanistic target of rapamycin kinase)
Diseases named in the same sentence as MTOR in open-access papers (continued):
Sharing a sentence is not in itself a finding about the gene and the disease.
cancer (continued). "Targeting the AMPK/mTOR pathway is an active area of research for developing cancer therapies that disrupt cancer cell metabolism and growth." (PMID 38002335, 2023). "Because mTOR activation is central for cell cycle progression, cell growth, cell proliferation and cell survival, it is often constitutively activated in cancers to sustain tumour growth." (PMID 37877351, 2023). "In contrast, its overexpression increases phosphorylation and activity of both TSC1 and TSC2, whereas increased phosphorylation of S6K1 and 4E-BP1 is observed in DYRK1A knockdown cancer cells—the effect inhibited by the mTOR-inhibiting drug rapamycin." (PMID 36982355, 2023). "So far, the majority of studies in the field of the effects of pathways in which mTOR are involved by activating these pathways have been for the benefit of cancerous conditions in cancer." (PMID 37280524, 2023). "mTOR is frequently improperly activated in human cancers and results in alteration of both mTORC1 and mTORC2 signaling pathways, leading to increased cell proliferation and decreased apoptosis." (PMID 36839989, 2023). "Better understanding of the complex regulatory mechanisms of the mTOR signaling pathway have been important in the development of mTOR inhibitors for treatment of cancer and in identifying predictors of response or resistance." (PMID 37046675, 2023). "GSEA analysis of bulk RNA sequencing data also demonstrated the activation of Myc and TGF‐β, activated pathways included cell cycles, MAPK, mTOR, and pathways in cancer were also verified in HPCs from 16 wpt by GSEA analysis." (PMID 37085918, 2023). "Although it has been previously established that doxycycline inhibits proinflammatory responses by acting via the mTOR pathway in cancer cell lines, its impact on the inflammasome pathway, particularly in the lungs, has not yet been evaluated." (PMID 37267267, 2023). "The PI3K/AKT/mTOR pathway is frequently activated in a wide variety of cancers including breast, gastric, ovarian, colorectal, prostate, glioblastoma and endometrial cancers." (PMID 36765661, 2023). "KEGG enrichment analysis revealed that the pathways most enriched for upregulated DEGs were pathways in cancer, cell cycle, microRNAs in cancer, mTOR signaling pathway and autophagy-animal." (PMID 37213521, 2023). "At the same time, the Huaier-induced decrease in p-mTOR also the downstream targets of this protein are severely dephosphorylated as a consequence, suggesting that Huaier extract effectively inhibits mTOR/S6K signaling, triggering autophagy in cancer cells." (PMID 38313074, 2023). "Mutations in the TSC1 and TSC2 genes of these complexes also activate the mTOR pathway and induce cancers." (PMID 37240915, 2023). "The stimulation of PI3K/AKT/mTOR signaling boosts cancer cells' capacity to grow, survive, and adapt metabolically, making it an attractive therapeutic target in cancer." (PMID 37287817, 2023). "PI3K/AKT/mTOR signaling pathway is one of the most frequent activated signaling pathways in cancers and promotes tumorigenesis." (PMID 37038184, 2023). "Signaling pathways determined by PI3K, AKT, and the mammalian target of rapamycin (mTOR) are critical for many features of cancer, such as cell growth, survival, metabolism, apoptosis, and angiogenesis." (PMID 37361222, 2023). "Increased activation of PI3K/Akt/mTOR signaling enhances proliferation, growth, and resistance to chemo- and immunotherapy in cancer cells." (PMID 37958470, 2023). "Everolimus is an inhibitor of mammalian target of rapamycin (mTOR) used in both transplantation and cancer treatment (breast, renal and neuroendocrine)." (PMID 37381038, 2023). "These bioactive compounds derived from natural products target the PI3K‐Akt–mTOR signaling pathway for cancer prevention and intervention." (PMID 35789211, 2023). "Multiple components of the signaling pathway that signals through mTOR are dysregulated in many cancer types." (PMID 36849137, 2023).
cancer (continued). "Activation of the mammalian target of rapamycin (mTOR) has often been observed in several types of cancer." (PMID 36768934, 2023). "Rapamycin’s ability to modify mammalian target of rapamycin (mTOR) signaling has projected benefits in transplantation, cancer therapy, and age-related disorders, even though the exact mechanisms and downstream consequences are still not completely explored." (PMID 37730584, 2023). "At present, many clinical trials of ATP competitive mTOR inhibitors for malignant tumors are under way." (PMID 37601696, 2023). "Metformin inhibits various intracellular signaling pathways, such as p38 MAPK, NF-kB, mTOR, and STATs in cancer cells; hence, we further examined the alteration of signaling pathways in A549-R." (PMID 37239373, 2023). "In our study, we found that cancer cells display distinct oncogenic alterations in the two risk groups (e.g., KRAS, PIK3CA, mTOR) that appear to directly induce metabolic changes." (PMID 36671486, 2023). "As a widespread regulator, circRNA seems reasonable to influence cancer progression by regulating the classic PI3K/AKT/mTOR signaling." (PMID 37046729, 2023). "SEMA3C enhances peritoneal dissemination by regulating putative cancer stemness and Gem resistance and activates phosphorylation of the Akt/mTOR pathway via c-Met." (PMID 37537633, 2023). "The mTOR pathway is a vital regulator in cancer cells to induce aerobic glycolysis, a crucial feature in UBUC." (PMID 37380971, 2023). "IPA revealed that multiple signaling pathways related to cancer development and apoptosis, such as the mTOR and IL-8 signaling pathways, were inhibited by GINS2." (PMID 36873736, 2023). "mTOR is a serine/threonine kinase downstream of PI3K-AKT that activates the transcription of multiple genes involved in cancer cell metabolism through mTOR complexes 1 and 2 (mTORC1 and 2)." (PMID 36982568, 2023). "Natural products were acting by the PI3K/Akt/mTOR signaling inhibition, showing their potency in cancer prevention and intervention." (PMID 35789211, 2023). "It was discovered through research into the impact of miR-224 on the growth of non-small cell lung cancer induced by cancer-associated fibroblast (NSCLC) that overexpression of SIRT3 can suppress miR-224 by activating AMPK and deactivating mTOR/HIF-1α." (PMID 37175631, 2023). "PIP3 can activate AKT, which in turn phosphorylates mTOR and a number of other targets, so that cancer develops in a direction that is more conducive to its survival." (PMID 37007127, 2023). "Our data demonstrate that mTOR regulates T cell exhaustion and have important implications for combination cancer therapies with PD-1 blockade." (PMID 36378537, 2023). "For instance, activation of the mitogen-activated protein kinase (MAPK) pathway, mTOR pathway and phosphatidylinositol 3-kinase/Akt signaling pathway have been implicated in OPN-associated cancer development." (PMID 38067407, 2023). "The therapeutic inhibition of the PI3K–Akt–mTOR pathway has previously been shown to radiosensitize a range of cancers, including CRC39,49–51." (PMID 37996663, 2023). "In cancer, PIK3C2A has been associated with the dysregulation of the phosphoinositide 3-kinase (PI3K)/AKT/mTOR pathway, which is frequently observed in various cancer types." (PMID 38067251, 2023). "Another phase 2 trial (NCT03190174) is investigating the biological activity of the sequential administration of nivolumab and the mTOR inhibitor ABI-009 in multiple types of cancer." (PMID 36765661, 2023).
cancer (continued). "The previous research showed that PGK1 can promote the proliferation of cancer by turning on the AKT/mTOR pathway in non-small-cell lung cancer." (PMID 37821504, 2023). "Dysregulation of the mTOR signal is illustrated in many human diseases, especially in various cancers." (PMID 37097377, 2023). "Being necessary for the promotion of growth and proliferation of adult stem cells, the PI3K/Akt/mTOR pathways are directly related to cancer." (PMID 36769263, 2023). "Sensitivity of cancer cells to carboplatin involves increased activity of mTORC1/2 signaling and DNA damage and repair functions, and targeting AKT/mTOR pathway impairs DNA repair responses, resulting in increased chemosensitivity in a variety of cancers." (PMID 36773034, 2023). "In a study of therapeutics targeting cancers, mTOR activation triggered CREB1 phosphorylation and accumulation, and inhibiting CREB1 led to a decrease in ATG7, which is a key factor in autophagy regulation." (PMID 37947633, 2023). "Although various factors activate mTOR signaling, this study focused on two mTOR regulatory mechanisms: anti-cancer drug-induced mTOR signaling and L-type amino acid transporter 1 (LAT1) (also referred to as SLC7A5)-induced mTOR activation." (PMID 36768934, 2023). "Preclinical data from our group and others have demonstrated the combination of a PI3K/mTOR inhibitor with a PARP inhibitor is synergistic in multiple cancer cell lines." (PMID 37644890, 2023). "Chronic CerS4 overexpression in MCF-7 cells also altered several critical signaling pathways, including Akt/mTOR, NF-κB, and β-catenin, which play essential roles in cancer development and progression." (PMID 37885013, 2023). "An increase in DNL is also linked to the activation of oncogenic signaling pathways, such as the PI3K/Akt/mTOR pathway, which is frequently dysregulated in cancer." (PMID 37692839, 2023). "The impairment of mitochondrial function via interfering certain signalling pathways, such as mTOR and CaMKII/Parkin/mitophagy, was targeted by several studies to tackle metabolic stress in CC cell lines, to inhibit the cancer cell growth." (PMID 36683048, 2023). "Parallelly, several cases of therapy-refractory cancer types are emerging day by day, where the mTOR pathway plays a vital role either by rescuing drug resistance or by distorting drug sensitivity." (PMID 37602330, 2023). "Previously, we showed that canagliflozin blocks mitochondrial complex‐I‐supported respiration leading to AMPK activation and suppression of the mTOR pathway in cancer cells." (PMID 37584455, 2023). "PI3K/Akt/mTOR also regulates transporters and in several cancers PI3K/Akt/mTOR signaling leads to transporter-mediated drug resistance." (PMID 36973040, 2023). "The study proved that OCMC polymeric Nps of MET decorated with WZB117 improved treatment efficacy by dual targeting the GLUT1 and mTOR pathways to alter cancer metabolism and improve BC management." (PMID 36850263, 2023). "Activation of the phosphatidylinositol 3-kinases (PI3Ks)/Akt/mammalian target of rapamycin (mTOR) pathway plays a vital role in cancer growth and survival and targeted therapies aimed to reverse endocrine resistance." (PMID 36902831, 2023). "Dual PI3K/mTOR inhibitors are considered critical in cancer therapy, and many dual PI3K/mTOR inhibitors are available and in use, such as dactolysisib, sarmotolysisib, and voltaricoxib." (PMID 37641116, 2023). "Numerous studies have shown that the mTOR signaling pathway mediated mitophagy and apoptosis in colon, ovarian, and other cancer cells." (PMID 37686278, 2023). "AMPK activation is conducive to the occurrence of various malignant tumors by inhibiting the proliferation of tumor cells, and it also promotes apoptosis by inhibiting the mTOR signaling pathway." (PMID 36647780, 2023). "Omipalisib (GSK2126458) is an oral dual PI3K/mTOR inhibitor that suppresses the growth and progression of cancer cells." (PMID 37046703, 2023).
cancer (continued). "The suppressed activation of the PI3K/Akt/mTOR signaling pathway by curcumin has been reported in many cancer cells, including GBM cells." (PMID 37298208, 2023). "The PI-3K–AKT–mTOR pathway is commonly activated in cancer, and a recent shRNA library screen identified mTOR as an essential kinase in a subset of SCLC." (PMID 36883564, 2023). "Down-regulation of PIK3CG can impede the PI3K/AKT/mTOR pathway that has been suggested as a possible therapy in cancer." (PMID 37243196, 2023). "Blocking the PI3K/AKT/mTOR signaling pathway with the dual PI3K/mTOR inhibitor BEZ235 repressesed cancer-promoting effect of FAP." (PMID 37752545, 2023). "The previous study reported that there was an abnormal PI3K/Akt/mTOR signaling pathway in a variety of malignant tumors." (PMID 37896137, 2023). "The mTOR multiprotein complex, mTOR1 is significantly deregulated in cancer including GBM, which has driven an increasing interest in rapamycin-based therapies including everolimus (RAD001)." (PMID 36302993, 2023). "In recent decades, numerous inhibitors related to the PI3K/AKT/mTOR signalling have made great strides in cancer treatment, like copanlisib and sirolimus." (PMID 37489050, 2023). "Results indicated that some cancer hallmarks were much more enriched in the high-risk score group, such as MYC and MTOR-related pathways." (PMID 38022584, 2023). "The mTOR kinase has been recognized as one of the master regulators of translation to meet the demand for cancer cells." (PMID 37779156, 2023). "The PI3K/AKT/mTOR pathway plays a fundamental role in cancer cell proliferation, survival, and metabolism, and is one of the most commonly disrupted pathways in malignancy." (PMID 37701204, 2023). "This further suggests that the PI3K/AKT/mTOR signaling pathway plays a key role in cancer inhibition mediated by RILP." (PMID 37789274, 2023). "The mTOR pathway, which regulates cell development, proliferation, and survival, is frequently dysregulated in cancer, and EVL, an mTOR inhibitor, is frequently utilized in a variety of malignancies." (PMID 37140396, 2023). "While intensely studied for its role in cancer, the role of mTOR signaling is just beginning to be uncovered in specific cell types that are implicated in neurodevelopmental disorders." (PMID 38201256, 2023). "For multiple types of cancers, NPs-based mTOR targeted therapies put forward potential therapeutic choices." (PMID 36597205, 2023). "The metastatic behavior of OS is also dependent on the PI3K/Akt/mTOR cascade, in which mTOR contributes to cellular transformation and poor cancer prognosis via its downstream effectors S6K1, 4EBP1 and eIF4E." (PMID 36839989, 2023). "Combining therapy with mTOR inhibitors with the glutaminase inhibitor CB-839 is beneficial in overcoming therapeutic resistance to certain other focused inhibitors in these cancers." (PMID 36851259, 2023). "It is reported that the effect of CK on cancer cells is related to the AMPK-mTOR/JNK pathway, the PI3K/Akt/mTOR pathway, and reactive oxygen species (ROS)." (PMID 37511939, 2023). "Activating mutations in key factors of the PI3K/AKT/mTOR pathway, such as PIK3CA, AKT, or MAP3K3, lead to the activation of PI3K signaling and uncontrolled cell proliferation in many human cancers." (PMID 37109059, 2023). "One such signaling pathway that has been shown to be altered in several types of human cancers is the phosphatidylinositol 3-kinase (PI3K)/AKT/mammalian target of rapamycin (mTOR) pathway." (PMID 37835462, 2023). "In this work, we show that lipid mediator formation is affected by 3D growth of cancer cells in a PI3K/mTOR- and MEK-1/ERK-dependent manner." (PMID 36849252, 2023).
cancer (continued). "It has been 24 years since rapamycin (sirolimus) was approved to mitigate solid organ transplant rejection and 16 years since mTOR (mammalian/mechanistic target of rapamycin) inhibitors reached patients as a cancer therapy." (PMID 38201496, 2023). "The PI3K/Akt/mTOR pathway has been shown to be aberrantly activated in many human cancers, including breast, lung, ovarian, pancreatic and gastric carcinomas." (PMID 36769122, 2023). "A nutrient-sensing pathway that is tightly linked to the PI3K/Akt pathway and is frequently disrupted in cancer is mTOR signaling." (PMID 37838167, 2023). "In cancer, abnormally (de)activated signaling pathways such as mTOR/PI3K-Akt and NFκB signaling stimulate tumor cells to proliferate aggressively, metastasize, and become even more resilient to therapy." (PMID 36902107, 2023). "KEGG-GSVA enrichment results also confirmed that the activities of pathways related to cancer cell proliferation and metastasis in the high group, such as the cell cycle, mTOR, VEGF, and JAK-STAT signaling pathways, were significantly increased." (PMID 36937841, 2023). "Recent studies revealed that Cu E inhibits proliferation and metastasis of cancer cells by causing cell-cycle arrest and apoptosis, as well as suppressing PI3K/Akt/mTOR, JAK/STAT3, and MAPK pathways." (PMID 37886957, 2023). "The PI3K/AKT/mTOR pathway is activated in a wide type of cancers, leading to tumor proliferation and therapeutic resistance." (PMID 37189349, 2023). "Quercetin increases apoptosis and autophagy in cancer by activating caspase-3, inhibiting the phosphorylation of Akt, mTOR, and ERK, lessening β-catenin, and stabilizing the stabilization of HIF-1α." (PMID 36926328, 2023). "It showed anti-cancer activity against PC-3 cells by inhibiting the Akt-mTOR pathway through the aryl hydrocarbon receptor." (PMID 36926328, 2023). "In the oral squamous cell carcinoma model, 6-shogaol induced cancer cell apoptosis by inhibiting the PI3K/AKT/mTOR signaling pathway." (PMID 37875983, 2023). "The secretion of IL-6 by transformed M2 TAMs promotes cancer cells to express more YAP1, K-Ras, β-catenin, NF-κB, and mTOR and thus enhances the percentage of cancer stem-like cells." (PMID 37124519, 2023). "As the upstream pathways of autophagy, the AMPK/mTOR and Phosphoinositide 3-kinase (PI3K)/ protein kinase B (AKT)/mTOR pathways critically regulate autophagy and are responsible for multiple cellular activities and cancer progression." (PMID 37355631, 2023). "The top cancer hallmarks that were suppressed by the combination were PI3K/AKT/mTOR signaling, apical junction proteins, G2/M checkpoint proteins, and E2F target proteins, while apoptosis and hypoxia were among the top cancer hallmarks that were upregulated." (PMID 36719376, 2023). "The earlier studies suggest that the generation of any irregularity in the PI3K/Akt/mTOR pathway can lead to the development of cancer." (PMID 36737760, 2023). "Considering the heavy treatment burden of cancer patients, the research on mTOR will continue to rise, which will result in progress in clinical treatment modalities." (PMID 37637052, 2023). "Although different targets for PA have been reported, the most significant target of PA in cancer cells is likely to be mTOR." (PMID 37190124, 2023). "Recently, the mTOR complex has been shown as a nutrient sensor in cancer metabolism which includes glucose, lipid, amino acids, nucleotides, growth factors, etc." (PMID 37779156, 2023). "While apoptosis had been identified as the primary mechanism through which the HDAC inhibitors promoted cancer cell death, autophagy promotion was also associated with a PI3K/Akt/mTOR pathway inhibition." (PMID 36766800, 2023). "To explore these vital questions, we focus on dysregulated PI3K/mTOR, a major brain cell growth pathway in differentiation, and MAPK, a critical pathway in proliferation, a hallmark of cancer." (PMID 37124926, 2023).